HBP1 (HMG-box transcription factor 1)
Description:
Transcriptional repressor that binds to the promoter region of target genes. Plays a role in the regulation of the cell cycle and of the Wnt pathway. Binds preferentially to the sequence 5'-TTCATTCATTCA-3'. Binding to the histone H1.0 promoter is enhanced by interaction with RB1. Disrupts the interaction between DNA and TCF4.
Tractability: PROTAC: UniProt records ubiquitination sites on it; ubiquitination databases record sites on it.
Gene: Protein-coding gene on chromosome 7 (107,168,961 to 107,202,529, forward strand). Ensembl gene ENSG00000105856.
Subcellular location: Nucleus
Subcellular location (Human Protein Atlas): Nuclear speckles
Gene Ontology:
Molecular function: protein binding; DNA-binding transcription factor activity, RNA polymerase II-specific; RNA polymerase II cis-regulatory region sequence-specific DNA binding; RNA binding
Biological process: regulation of cell cycle; regulation of transcription by RNA polymerase II; regulation of DNA-templated transcription
Cellular component: nuclear speck; chromatin; nucleus
Genetic constraint (gnomAD): Loss-of-function variants: 3 observed, 11.43 expected, observed/expected ratio (o/e) 0.26, 90% interval 0.12 to 0.68. The upper end of that interval is the gene's LOEUF score, 0.68, which puts it in group 2 of 6, group 1 being the genes least tolerant of losing a copy. Missense variants: 120 observed, 155.96 expected, observed/expected ratio (o/e) 0.77, 90% interval 0.66 to 0.89. Synonymous variants: 52 observed, 54.35 expected, observed/expected ratio (o/e) 0.96, 90% interval 0.76 to 1.21.
Homologues: Orthologues: chimpanzee HBP1 (100% identical), macaque HBP1 (99% identical), pig HBP1 (97% identical), dog HBP1 (96% identical), rabbit HBP1 (95% identical), guinea pig HBP1 (95% identical), mouse Hbp1 (95% identical), rat Hbp1 (93% identical), tropical clawed frog hbp1 (76% identical), zebrafish hbp1 (64% identical).
Diseases named in the same sentence as HBP1 in open-access papers:
HBP1 is named in the same sentence as 71 diseases in open-access papers, as found by Europe PMC text mining. Sharing a sentence is not in itself a finding about the gene and the disease. The quoted sentences say what the papers report.
breast carcinoma (23 papers, 2011 to 2025). "A previous study demonstrated that over half of the tested breast cancer samples (15 of 22) had reduced HBP1 mRNA levels and HBP1 mutations/variants were associated with invasive breast cancer." (PMID 24895061, 2014). "This study identified a correlation between inactivating HBP1 mutations and invasive breast cancers in clinical breast cancer samples." (PMID 23533807, 2013). "HBP1 expression is inhibited in a variety of human malignancies, and HBP1 gene mutation is found in breast cancer, suggesting that the mutation or loss of HBP1 may be one of the causes of cell transformation." (PMID 33794968, 2021). "The HMG-box transcription factor 1/TIMP metallopeptidase inhibitor 3/PTEN axis inhibits the tumorigenesis of breast cancer and promotes the sensitivity of breast cancer to radiotherapy and hormone therapy." (PMID 39991583, 2025). "Our lab discovered and characterized the HBP1 transcriptional repressor in the context of cellular senescence and Wnt signaling in breast cancer and other functions." (PMID 34358226, 2021). "Downregulating HBP1 promotes the migration and invasion of oral squamous cell carcinoma and breast cancer." (PMID 34777463, 2021). "For example, overexpressed miR-17-5p promoted the migration and invasion of breast cancer cells via direct binding to the 3′UTR of HMG box-containing protein 1 (HBP1) and subsequent activation of the Wnt/β-catenin pathway." (PMID 34728784, 2021). "HMG-box transcription factor 1 (HBP1) had been described as a negative regulator of the Wnt/β-catenin signaling in many cancers, including breast cancer, osteosarcoma, glioma, and colorectal carcinoma." (PMID 32850392, 2020). "Sears and co-workers also showed that HBP1 inhibits the activity of Myc, a gene often overexpressed in breast cancer." (PMID 27129219, 2016). "Statistical analysis on breast cancer patient database revealed a direct relationship between reduced HBP1 levels (or increased Wnt signaling) and increased cancer recurrence." (PMID 23533807, 2013). "Further evidence in support of a role of Wnt signaling in recurrent and invasive breast cancers came from the study on HBP1, the transcriptional repressor of Wnt signaling." (PMID 23533807, 2013). "We noticed that HBP1, which has been identified as a miR-17 target in human breast cancer cells was included in the leading edge genes subset whose expression increases in response to HMBA in 745A#44 cells." (PMID 23056458, 2012). "It has been shown that overexpression of miR-17 promotes human breast cancer cell migration and invasion through downregulation of HBP1." (PMID 21980462, 2011). "High levels of Klhl24, Hbp1, Crebrf, Ypel2, CD22 and Ypel3 were correlated with better outcomes, whereas lower levels of Gdf15, Cdc25a, Ddit4 and Psat1 were associated with better prognosis in breast cancer patients." (PMID 34990474, 2022). "Intriguingly, we observed a statistically significant inverse correlation between MDM2 and HBP1 protein levels in human uterine cervix cancer, thyroid cancer, and breast cancer with high expression of MDM2 (compared with carcinoma versus para-carcinoma) using immunohistochemistry assay." (PMID 30816344, 2019). "In addition, HBP1 gene lies within the chromosome 7q31.1 that is frequently deleted in many tumours, such as colon cancer, breast cancer and myeloid leukaemia." (PMID 24895061, 2014). "Similarly, Fli-1 has been shown to contribute to the high malignancy of the breast cancer cell line MDA-MB231 whereas another study independently showed the inhibition of Hbp1 by miR-17 in the same cells." (PMID 23056458, 2012). "Suppression of HBP1 could also promote human breast cancer cell migration and invasion." (PMID 29663730, 2018). "EGCG induced HMG-box transcription factor 1 (HBP1) transcriptional repressor, resulting in blockage of the Wnt/β-catenin pathway and inhibition of both breast cancer cell tumorigenic proliferation and invasiveness." (PMID 27483305, 2016).
breast carcinoma (continued). "Recently, HMG box-containing protein 1 (HBP1) and zinc-finger and BTB domain containing 4 (ZBTB4) were reported to be targets of miR-17-92 and to be correlated with the prognosis in breast cancer." (PMID 22952885, 2012). "Also, the miR-17-92 cluster is known to regulate cell migration, invasion, and metastasis in breast cancer by regulating ROCK and the HBP1/β-catenin pathway." (PMID 22353773, 2012). "We also have tested HBP1 protein in non-NPC cells by western blotting, which is lowly expressed in liver cancer, breast cancer and ovarian cancer cells." (PMID 29367693, 2018).
glioma (8 papers, 2018 to 2024). A benign or malignant brain and spinal cord tumor that arises from glial cells (astrocytes, oligodendrocytes, ependymal cells). "The tumor suppressor role of HBP1 has been reported in some malignancies, such as oral cancer and glioma." (PMID 30619295, 2018). "In addition, increased levels of MIR-29a and MIR-92a within the hypoxic glioma-derived EVs decrease the expression of the high-mobility group box transcription factor 1 (Hbp1) and protein kinase CAMP-dependent type I regulatory subunit alpha (Prkar1α) genes in MDSCs, respectively." (PMID 36010994, 2022). "Previous studies have identified several downstream targets of miR-155-5p that function as tumor suppressors in glioma progression, including FOXO3a, MXI1, and HBP1." (PMID 35986010, 2022).
lung carcinoma (8 papers, 2014 to 2022). "It has been reported that the hypermethylation of HBP1 promoter is responsible for the loss of HBP1 in human non‐small cell lung cancer (NSCLC), which results in the poor prognosis of cancer through promoting β‐catenin activity." (PMID 33769664, 2021). "Overexpression of AFAP1‐AS1 inhibited cell apoptosis but enhanced the proliferation and migration of lung cancer cells by partially repressing HBP1 expression through recruiting LSD1 to the HBP1 promoter regions." (PMID 35379783, 2022). "Based on RNA sequencing from the database, HBP1 and p21 were frequently down-regulated in uterine cancer, colon cancer, rectum cancer, lung cancer, liver cancer, and stomach cancer, whereas EZH2 was frequently up-regulated in these cancers." (PMID 27129219, 2016). "Our study provides a link for the transactivation of nuclear β-catenin through epigenetic inactivation of HBP1 in lung cancer." (PMID 24895061, 2014). "To verify the role of HBP1 in transcriptional regulation of β-catenin/TCF in lung cancer, we examined the effect of ectopically expressed HBP1 in A549 cells." (PMID 24895061, 2014). "Altogether, our data suggested that HBP1 expression plays an important role in suppressing β-catenin transactivation in lung cancer." (PMID 24895061, 2014). "Our data from cellular and clinical models suggest that HBP1 is a suppressor of cancer progression, making it a potential prognostic predictor and therapeutic target to attenuate lung cancer progression." (PMID 24895061, 2014). "To further confirm the reciprocal relationship between HBP1 expression and β-catenin activity in lung cancer, we examined whether HBP1 knockdown would affect β-catenin/TCF activity and increase c-MYC and cyclin D1 expression." (PMID 24895061, 2014). "The search for antagonists or agonists of the HBP1 may also lead to the discovery of compounds that can potentially be used for lung cancer treatment." (PMID 24895061, 2014). "Therefore, miR-155-5p could promote lung cancer development and metastasis by inhibiting the HBP1 expression." (PMID 26543233, 2015). "What’s more, they found four target genes of miR-155 including HBP1, TJP1, SMAD5 and PRKAR1A involved in the oxidative stress process of lung cancer." (PMID 31727002, 2019).
atherosclerosis (7 papers, 2016 to 2024). A disease characterized by the build-up of fatty material and calcium deposition in the arterial wall resulting in partial or complete occlusion of the arterial lumen. "More specifically, mRNA targets such as Bcl6, Hbp1, Mst2, and Socs1, which are reduced in atherosclerosis have been shown to play a protective role against the disease’s development." (PMID 30369883, 2018). "Our previous research elucidated the role of miR-19a-3p in atherosclerosis through the miR-19a/HBP1/MIF pathway upon that foundation, the current study aimed to investigate the expression levels of HOTAIR in both the plasma of atherosclerosis patients and foam cells." (PMID 38250607, 2024). "Thus there is a forward feedback loop during atherosclerosis: TNF-α stimulates the expression of miR-19a to suppress HBP1 and subsequently elevate MIF production, which in turn increases TNF-α secretion." (PMID 28935967, 2017). "In the present work, we ascertain HBP1 as a novel target gene of miR-19a in atherosclerosis." (PMID 28935967, 2017). "The biological function and their roles in atherosclerosis progression for the other genes, including DAZAP2, ARL6ip, CDK7, LIMS, HBP1, and DNAJB6, remain to be investigated." (PMID 35795669, 2022). "By targeting the miR-19a-3p-HBP1-MIF pathway, HOTAIR represents a potential therapeutic target for modulating the inflammatory response and foam cell formation, offering promising avenues for the development of novel treatments for atherosclerosis." (PMID 38250607, 2024). "The HMG-Box Transcription Factor 1 (HBP-1) gene is a known target for miR-19a which leads to an increase in macrophage migration inhibiting factor (MIF) that links miR-19a overexpression to both acute coronary syndrome and atherosclerosis." (PMID 36071532, 2022). "Combined with present and previous studies, we uncovered the involvement of HOTAIR in atherosclerosis, at least in part, we demonstrate that HOTAIR alleviates the formation of foam cell and inflammatory reaction by inhibiting miR-19a-3p in atherosclerosis through TNF-α/miR-19a/HBP1/MIF pathway." (PMID 38250607, 2024).
colorectal cancer (6 papers, 2016 to 2021). A primary or metastatic malignant neoplasm that affects the colon or rectum. "Wan et al41 also demonstrated the oncogenic role of miR‐155 in colorectal carcinoma by suppressing the expression of HBP1." (PMID 33769664, 2021). "In oral squamous cell carcinoma, miR-146b inhibition suppressed migration, cell proliferation, and invasion via binding and downregulating HBP1 expression and in the colorectal cancer miR-576-5p-targeted Wnt5a-mediated Wnt/β-catenin signaling pathway by inducing epithelial-to-mesenchymal transition." (PMID 34804161, 2021). "Recently, NRIP2 was shown to regulate colorectal cancer-initiating cell renewal as a Wnt pathway interactor, functioning as a novel molecule that cooperates with RORβ and HMG box-containing protein 1 (HBP1) to modulate Wnt activity." (PMID 35004680, 2021).
oral cancer (6 papers, 2014 to 2020). "To illustrate FOXO1 regulation of HBP1 expression in oral cancer, first, we examined if HBP1 expression levels are in concert with FOXO1 levels." (PMID 28099936, 2017). "Here, we showed that HBP1 can function as a downstream effector of FOXO1-mediated growth inhibition in oral cancer; HBP1 knockdown alleviated the suppressive effect of FOXO1 on colony formation." (PMID 28099936, 2017). "The results indicated that HBP1 knockdown potently promoted malignant phenotypes of oral cancer and the suppressive effect of FOXO1 on cell growth, colony formation, and invasion was alleviated upon HBP1 knockdown in invasive oral cancer cells." (PMID 28099936, 2017). "In a previous study, we demonstrated that HBP1 protein expression was down-regulated upon ectopic expression of a constitutive form of Akt in oral cancer cells." (PMID 28099936, 2017). "In a previous study, we demonstrated that HBP1 is a downstream effector of the EGFR (epidermal growth factor receptor))/Akt pathway in oral cancer." (PMID 28099936, 2017). "Conversely, ectopic or chemical-induced expression of HBP1 results in growth arrest, apoptosis, or differentiation in cancer cell lines, including oral cancer." (PMID 28099936, 2017). "Together, the current study provided evidence that FOXO1 and HBP1 function coordinately as tumor suppressors in invasive oral cancer." (PMID 28099936, 2017). "Ectopic expression of FOXO1 led to increased HBP1 promoter activity and HBP1 expression in oral cancer cells." (PMID 28099936, 2017). "In the present study, we further found that the PI3K inhibitor LY294002 significantly up-regulated HBP1 expression with a concomitant decrease in FOXO1 phosphorylation in HSC-3 oral cancer cells." (PMID 28099936, 2017). "Previously, we demonstrated that HBP1 functions as a downstream effector of the EGFR/Akt signaling pathway in oral cancer." (PMID 28099936, 2017). "FOXO1-induced activation of the 2-kb HBP1 promoter was also observed in HSC-3 oral cancer cells, and the induction was abolished when co-transfected with FOXO1-specific siRNA." (PMID 28099936, 2017). "Ectopic overexpression of constitutively active FOXO1 (FOXO1-AAA) significantly suppressed colony growth in HSC-3 oral cancer cells; however, HBP1 knockdown alleviated the suppressive effect of FOXO1-AAA on colony formation." (PMID 28099936, 2017). "Taken together, our data provide evidence for HBP1 as a direct downstream target of FOXO1 in oral cancer malignancy." (PMID 28099936, 2017). "Furthermore, both FOXO1 and HBP1 mRNA levels were significantly lower in three EGFR over-expressing oral cancer cells tested than the normal human oral keratinocyte (HOK)." (PMID 28099936, 2017). "Similarly, knockdown of FOXO1 expression with FOXO1-specific siRNA led to reduced HBP1 expression in TW206 oral cancer cells with high level of endogenous FOXO1." (PMID 28099936, 2017). "FOXOs are directly modified by Akt phosphorylation for subsequent degradation; however, how HBP1 expression is down-regulated by Akt remains unclear in oral cancer." (PMID 28099936, 2017). "Next, we examined whether FOXO1-mediated expression of HBP1 modulates tumorigenic growth and metastatic potential in oral cancer." (PMID 28099936, 2017). "In the current study, we found a decreased FOXO1 mRNA level in invasive oral tumor specimen, and the combination of decreased mRNA expression levels of FOXO1 and HBP1 may predict invasiveness of oral cancer." (PMID 28099936, 2017). "Furthermore, the biological significance of FOXO1-mediated HBP1 expression was demonstrated by the experiments of colony formation and cell invasion in oral cancer cells." (PMID 28099936, 2017). "In addition, treatment with N-acetylcysteine, an anti-cancer compound, suppresses cell growth by increasing the expression of HBP1, but HBP1 knockdown attenuated growth arrest and apoptosis in oral cancer." (PMID 24895061, 2014).
oral cancer (continued). "Hence, we studied whether FOXO1 activation of the HBP1 promoter is also under the control of the upstream regulator Akt in the HSC-3 oral cancer cell line with an aberrant activation of the EGFR/PI3K pathway." (PMID 28099936, 2017). "A recent study by Chan also indicated that HBP1 acted as a direct downstream target of FOXO1, and potently suppressed the phenotypes of oral cancer." (PMID 32850392, 2020). "For example, HBP1 induction by ROS scavenger, NAC, decreases cell viability and induces apoptosis in oral cancer cells and this effect was mediated by inhibition of Akt activation." (PMID 32406610, 2020). "However, the relationship between FOXO1 and HBP1 in oral cancer remains unclear." (PMID 28099936, 2017). "Taken together, these data support HBP1 as a downstream target of FOXO1, which contributes to FOXO1-mediated inhibition of malignancy in oral cancer." (PMID 28099936, 2017). "Hence, the current study is aimed at investigating the putative transcriptional regulation of HBP1 by FOXO1 and, collectively, the biological significance of FOXO1 and HBP1 in oral cancer." (PMID 28099936, 2017). "These clinical data suggest that a combination of low HBP1 and low FOXO1 status might determine oral cancer malignancy, and that HBP1 and FOXO1 expression might be coordinately regulated." (PMID 28099936, 2017). "Indeed, when we tested the correlation between HBP1 and FOXO1 expression in aggressive oral cancer specimens, we found that HBP1 mRNA levels were positively correlated with FOXO1 mRNA levels in invasive oral cancer." (PMID 28099936, 2017). "Subsequently, a recent report illustrated that HBP1 is direct target of growth factors-mediated PI3K/Akt/FOXO pathway in various types of cancer; however, whether or not FOXO1 regulates HBP1 expression in oral cancer remains unclear." (PMID 28099936, 2017).